CTNNB1 (catenin beta 1)
Diseases named in the same sentence as CTNNB1 in open-access papers (continued):
Sharing a sentence is not in itself a finding about the gene and the disease.
liver cancer (116 papers, 2011 to 2026). An epithelial or non-epithelial malignant neoplasm that arises from the liver. "In summary, ARID1A loss and CTNNB1 activation synergistically promote liver cancer by enhancing β‐catenin signaling and tumorigenic potential, driven by AA‐induced mutational co‐occurrence." (PMID 41133886, 2026). "To assess how AXIN1-deficiency drives HCC, we introduced HCC-associated AXIN1 and CTNNB1 mutations in human liver cancer cells and liver-derived organoids." (PMID 41550750, 2026). "To address these issues, we introduced a variety of HCC-associated AXIN1 mutations as well as activating CTNNB1 mutations in the liver cancer cell line Huh7, HEK293T cells, and mouse liver progenitor organoids." (PMID 41550750, 2026). "As a case study, we investigated liver cancer, a disease with significant treatment challenges, by examining the traditionally undruggable CTNNB1 mutation." (PMID 40293950, 2025). "Our case study in liver cancer, particularly on the interaction between CTNNB1 mutations and sorafenib, exemplifies the practical utility of the pipeline." (PMID 40293950, 2025). "CTNNB1 mutation has been reported as an indicator of good prognosis of liver cancer and a new target for treatment." (PMID 39972122, 2025). "Among the newly identified immunopeptidome-evidenced neoantigens, we highlight shared neoantigens in colon cancer derived from frameshift mutations in LARP4B, as well as a missense mutation, CTNNB1 T41A, a driver gene in liver cancer." (PMID 40672284, 2025). "In summary, our findings demonstrate that CTNNB1 mutations are associated with enhanced sensitivity to sorafenib in liver cancer, highlighting a potential therapeutic strategy for targeting this vulnerable patient subset." (PMID 40293950, 2025). "Liver cancer tissue commonly harbors CTNNB1 mutations, which encode β-catenin and are associated with poor differentiation." (PMID 40943055, 2025). "In a case study on liver cancer, we identified and validated an association between CTNNB1 mutations and enhanced sensitivity to sorafenib, highlighting a potential therapeutic strategy for this challenging mutation." (PMID 40293950, 2025). "We turned our attention to CTNNB1, the sixth-ranked hub gene in our constructed network and one of the most frequently mutated genes in liver cancer." (PMID 40293950, 2025). "One of the mutations in our study occurred in CTNNB1, one of the most frequently mutated proto-oncogenes in liver cancer, while the other mutation occurred in SLTM, a regulator of RNA processing." (PMID 38497929, 2024). "For example, a high incidence of mutations in the β-catenin gene (CTNNB1) has been observed in liver cancer, endometrial cancer, and colorectal cancer (CRC)." (PMID 36983771, 2023). "The Ctnnb1 gene was of particular interest due to its high frequency of mutations in liver cancer and its crucial role as the key effector in canonical Wnt-signalling." (PMID 37907668, 2023). "A previous study classified liver cancer into four immune subtypes: tumor-associated macrophages, CTNNB1, cytolytic activity (CYT), and regulatory T cells (Tregs)." (PMID 36627693, 2023). "For instance, 13.4 to 19% of liver cancer patients infected with HBV harbor CTNNB1 mutations in tumor lesions, suggesting a potential collaboration of these two pathological events in liver cancer development." (PMID 36122209, 2022). "A total of 13.4 to 19% of liver cancer patients infected with HBV harbor CTNNB1 mutations in tumor lesions." (PMID 36122209, 2022). "CTNNB1, encoding β-catenin protein, is the most frequently altered proto-oncogene in hepatic neoplasms." (PMID 36122209, 2022). "β-Catenin encoding gene CTNNB1 is known as the most frequently mutated proto-oncogene in liver cancer." (PMID 36122209, 2022).
liver cancer (continued). "Larger, multi-center studies of the correlation between CTNNB1 mutations in urine cfDNA and HCC tumor status are needed to evaluate the potential clinical utility of urinary CTNNB1 mutation detection in liver cancer management and precision medicine." (PMID 34441409, 2021). "Activating mutations of the primary Wnt signal effector β-catenin (CTNNB1) is one of the most frequent events (15.9–32.8%) identified in liver cancer by genome-wide studies." (PMID 34083580, 2021). "Mutations to APC and CTNNB1 are the most frequent mutations in colon and liver cancer, respectively, and are thought to initiate cancer." (PMID 32486480, 2020). "Analysis of TCGA database revealed that CTNNB1 (β-catenin gene) is the third most mutated gene in liver cancer patients (24% of cases in cohort)." (PMID 32547703, 2020). "Reflecting the involvement of this module in liver cancer patients, we observed that frequency of CTNNB1 mutation tend to be higher in GATA4-low patients than in GATA4-high cohorts." (PMID 31903133, 2020). "This mirrors our previous finding of sex-biased CTNNB1 mutation frequency in liver cancer from TCGA exome sequencing data, with similar effect sizes (male: 33% vs. female: 12%11)." (PMID 32859912, 2020). "For instance, colorectal and hepatic cancers display activating mutations in the CTNNB1 gene encoding β-catenin, or inactivating APC and AXIN gene mutations." (PMID 31412666, 2019). "Mutations in CTNNB1, the gene encoding β-catenin, are common in colon and liver cancers, the most frequent mutation affecting Ser-45 in β-catenin." (PMID 31690625, 2019). "For the CTNNB1:S33C mutation, the total number of HLA-A*02:01 patients in the US is expected to be 364, from uterine corpus, prostate and liver cancer types." (PMID 31775766, 2019). "These missense mutations in exon 3 of CTNNB1 represent a subgroup of liver cancer with distinctive clinical and pathological features." (PMID 29541410, 2018). "Recently, it was demonstrated that HCCs harboring somatic missense mutations in exon 3 of CTNNB1 represent a subgroup of liver cancer with distinctive clinical and pathological features." (PMID 29541410, 2018). "The liver cancer-specific signature 16, associated with alcohol, displays a unique feature of transcription-coupled damage and is the main source of CTNNB1 mutations." (PMID 29101368, 2017). "Genes associated with concordant BRG1/BRM regulation that both decrease following BRG1/BRM loss were associated with genes upregulated in hepatoblastoma (CAIRO_HEPATOBLASTOMA_UP) or liver cancer with CTNNB1 mutations (CHIANG_LIVER_CANCER_SUBCLASS_UP)." (PMID 29273066, 2017). "When we selected variants listed in the COSMIC database and labeled them as the same cancer type, most were common variants, while a missense variant in PARP4 of stomach cancer was a shared variant and CTNNB1 of liver cancer was a private variant." (PMID 27010638, 2016). "Previous analysis of the gene expression profile of a panel of 84 liver cancer-specific genes in C/EBPα-saRNA-transfected HepG2 cells showed that most tumor genes including CTNNB1 (encoding β-catenin) and EGFR involved in EMT were down-regulated." (PMID 27050434, 2016). "For example, we found an apparent discrepancy in the presentation of recurrent somatic mutations of CTNNB1 (D32H and S37C) in liver cancer." (PMID 27010638, 2016).
liver cancer (continued). "Of note, the majority of the cases displayed mutations in exon 3 which is similar to CTNNB1 mutations identified in liver cancers." (PMID 26431491, 2015). "In this study, we surveyed mutations in the oncogenes known to be important in liver cancer and found that CTNNB1 is the predominantly mutated oncogene in Chinese HCC patients." (PMID 24798046, 2014). "Although the CTNNB1 mutation represents an important event leading to the tumorigenesis of hepatocytes, a mouse model overexpressing the liver-cancer associated β-catenin mutant showed that β-catenin itself was not sufficient to induce HCC." (PMID 24798046, 2014). "Notably, in LIHC, mutations in CTNNB1, which encodes β-catenin, drive aberrant activation of the Wnt/β-catenin signaling pathway, contributing to liver cancer progression." (PMID 40936932, 2025). "The connection between IGSF8 and CTNNB1 mutations in liver cancer suggests that IGSF8 could influence the regulation of Wnt signaling, possibly affecting tumor cell growth or differentiation." (PMID 40936932, 2025). "A more detailed analysis of how PTEN and CTNNB1 mutations influence liver cancer is needed." (PMID 39769068, 2024). "Furthermore, CTNNB1 mutations play a broader role in liver cancer by activating the Wnt/β-catenin pathway, which is further influenced by the overexpression of Glypican 3 (GPC3)." (PMID 39684755, 2024). "Moreover, in the pediatric liver cancer hepatoblastoma, CTNNB1 is the most recurrently mutated gene, with a frequency of 50–90%, which leads to consider CTNNB1 as a driving proto-oncogene." (PMID 37190050, 2023). "Liver cancer predominantly has mutations in CTNNB1 (25%) and AXIN1 (8%) genes." (PMID 36983771, 2023). "More importantly, CTNNB1 gain-of-function mutations are detected in more than 20% liver cancer." (PMID 36122209, 2022). "CTNNB1 mutation has also been reported in other tumors like liver cancer." (PMID 36539683, 2022). "CTNNB1 is the most frequently mutated proto-oncogene in liver cancer." (PMID 36122209, 2022). "CTNNB1‐activating mutations are identified in ~ 11–41% of liver cancers." (PMID 31955511, 2020). "Given that MYC amplification and CTNNB1 mutation are the driver alterations in liver cancer, we thus detected whether these two TFs influenced RUVBL2 expression." (PMID 31572066, 2019). "CTNNB1 mutations have been identified in about 20 - 40% of liver cancers." (PMID 27276713, 2016). "Thus, our findings strongly suggest the existence of a SL interaction between HGS and oncogenic CTNNB1 in HuH6 and HCT116 cells; nonetheless, further investigation is required to validate HGS as a new therapeutic target for liver cancers with CTNNB1 mutations." (PMID 26715116, 2015). "According to the whole genome sequencing analysis using liver cancer samples, intrinsic immunosuppression, a major barrier to the enhancement of immunotherapy, is driven by the mutually exclusive mechanisms of tumor-associated macrophages, Tregs, CTNNB1 mutation, and cytolytic activity." (PMID 37880538, 2023). "However, the CTNNB1 mutation is sufficient to cause liver cancer in zebrafish." (PMID 36122209, 2022).
liver cancer (continued). "Moreover, western blotting revealed that the expression of β-catenin in liver cancer cells decreased in both a time- and dose-dependent manner.The β-catenin protein, which is encoded by the CTNNB1 gene, plays an important role in canonical Wnt pathway signalling." (PMID 27010735, 2016). "To examine the over-representation of CTNNB1 mutations in HCC, we replaced Ctnnb1ex3/WT with an Apcfl/fl allele in our WNT–MYC liver cancer model." (PMID 41261129, 2026). "Next, we investigated the relationship between the expression levels of C5aR1, HDAC7, and CTNNB1 in liver cancer cases from TCGA database." (PMID 39736396, 2025). "The MIDN/CTNNB1/MMP9 axis promotes liver cancer progression via inducing a suppressive tumour immune microenvironment." (PMID 40111059, 2025). "Hepatoblastoma, the most prevalent pediatric liver cancer, almost always carries a WNT-activating CTNNB1 mutation, yet exhibits notable molecular heterogeneity." (PMID 39567475, 2024). "CTNNB1 is an important driver gene for liver cancer and hence their removal highlights the disease subtype." (PMID 39040139, 2024). "It has been reported that patients with a higher incidence of CTNNB1 changes in liver cancer presented with smaller tumor sizes and well-differentiated tumors." (PMID 37081465, 2023). "Activating mutation of CTNNB1 (encodes β-catenin) occurring in 37% of HCC is thought to support the growth and transformation of liver cancer stem cells." (PMID 36276076, 2022). "Through activation of Wnt signaling pathway, CTNNB1 involves in the early process of malignant tumors, including liver cancer, gastric cancer and EC with high incidence, which are all present in ectopic expression of CTNNB1." (PMID 36457747, 2022). "Here we show that a combination of oncogenes that is characteristic of liver cancer (CTNNB1, TERT, MYC) induces senescence in human fibroblasts and primary hepatocytes." (PMID 34302118, 2021). "The current findings indicate that STAT3 and CASP3 are related to liver cancer, while NOTCH1 and CTNNB1 are associated with pancreatic cancer." (PMID 35154607, 2021). "Mutations in WNT/β-catenin pathway coding genes such as CTNNB1, AXIN and APC are found in colorectal and hepatic cancers and are known to drive tumorigenesis." (PMID 31412666, 2019). "Of the associations involving signatures linked to extrinsic mutational processes, signature 4, linked to smoking, was associated with KRAS G12C (CCA > CAA) in lung adenocarcinoma and with CTNNB1 D32Y (TCC > TAC) in liver cancer." (PMID 29748584, 2018). "From this dataset, we found that the CTNNB1 subtype of liver cancer had a significantly lower expression of DAPK1 compared to other subtypes of liver cancer (Mann–Whitney U test, p = 0.008)." (PMID 28740751, 2017).
liver cancer (continued). "CTNNB1 gene, expressing β-catenin, and AXIN1 and AXIN2 genes, encoding for components of β-catenin degradation complex, are frequently mutated in liver cancers." (PMID 26943571, 2016). "In the RT-PCR analysis, we found that in both of the two liver cancer cell lines, the expression of CTNNB1 and SMAD4 was greatly inhibited by PS341 while the other four stemness-related genes remained almost the same (top)." (PMID 26915315, 2016). "Nucleotide changes affecting exon 3 of CTNNB1 gene were identified in 33 out of 134 (24.6%) liver cancer cases." (PMID 27276713, 2016). "One of these genes (HGS) is an SL partner of oncogenic β-catenin in colorectal HCT116 cancer cells, suggesting that the LS interaction between HGS and CTNNB1 is not limited to liver cancer." (PMID 26715116, 2015). "Consistent with its enrichment for CTNNB1 mutations (69%), lncRNA profile of the CTNNB1-enriched EEC subgroup was highly similar to that of the CTNNB1-enriched liver cancer subgroup." (PMID 26431491, 2015). "To investigate whether ARID1A loss and β‐catenin activation synergistically drive liver cancer, we analyzed the co‐occurrence of ARID1A and CTNNB1 mutations in AA‐exposed human HCC samples." (PMID 41133886, 2026). "The high expression of CTNNB1 in liver cancer means poor prognosis." (PMID 40111059, 2025). "Cai and colleagues proposed that targeting MMP-9 in CTNNB1 mutant liver cancers could restore CD8+ T cell-mediated antitumor immunity and enhance the efficacy of anti-PD-1 therapy." (PMID 40180907, 2025). "The Liver Cancer Cell Lines Database records indicate that MHCC-97H cells have a CTNNB1 mutation, whereas Hep3B cells do not." (PMID 40593458, 2025). "The correlation of MIDN and CTNNB1 suggested that MIDN might be an important regulator in liver cancer." (PMID 40111059, 2025). "In addition, in the Kaplan‒Meier survival analysis of the TCGA_LIHC data derived from liver cancer patients, alterations in ADAR1 and CTNNB1 were associated with a poorer prognosis than that obtained for patients without these alterations." (PMID 36599932, 2023). "Even though CTNNB1 is the most common mutated proto-oncogene, the significance of hyperactive β-catenin in liver cancer was not well documented." (PMID 36122209, 2022). "Moreover, AKT2 expression is positively corelated with CTNNB1 expression in human liver cancer samples in The Cancer Genome Atlas (TCGA)." (PMID 36122209, 2022). "In addition, CTNNB1 was also found to be closely related to a variety of tumor diseases such as liver cancer, gastrointestinal carcinoma and endometrial carcinoma." (PMID 36338963, 2022). "Overexpression of a mutant Ctnnb1 and Myc oncogene have been used to generate liver cancer models." (PMID 33837189, 2021).